XPO1 (exportin 1)
Diseases named in the same sentence as XPO1 in open-access papers (continued):
Sharing a sentence is not in itself a finding about the gene and the disease.
chronic lymphocytic leukemia (15 papers, 2017 to 2025). "Overexpression of mutation of XPO1 has been implicated in various hematologic malignancies including chronic lymphocytic leukemia (CLL), primary mediastinal B-cell lymphoma (PMBL), classical Hodgkin lymphoma (cHL), and DLBCL." (PMID 40806458, 2025). "XPO1 E571K, a hotspot mutation in chronic lymphocytic leukemia (CLL) and PMBL, was also frequently identified in cases with MC signatures and was usually accompanied by the BCL6-trans signature." (PMID 32736575, 2020). "Large-scale genomic analyses of human cancers identified mutational hotspots in the XPO1 gene and also recurrent heterozygous XPO1 mutations in a variety of cancer types, including chronic lymphocytic leukemia (CLL), Hodgkin’s lymphoma, and esophageal carcinoma." (PMID 40872651, 2025). "Overexpression of XPO1 is associated with poor prognosis in solid tumor cancers, while single-point mutations have been identified and associated with Hodgkin’s lymphoma and chronic lymphocytic leukemia (CLL)." (PMID 40148556, 2025). "These mutations impact cargo binding affinity to XPO1, resulting in altered gene expression, and are validated oncogenic mutations, as the E571 XPO1 mutation has been shown to drive an accelerated rate of leukemogenesis in mouse models of chronic lymphocytic leukaemia (CLL)." (PMID 40291981, 2025). "In chronic lymphocytic leukemia (CLL) cells, the situation is more complex since the mutation does not change SINE efficacy but reverses the resistance to selinexor and ibrutinib imposed by the overexpression of XPO1." (PMID 36727672, 2023). "XPO1 mutation is found in almost 15–25% of primary mediastinal B‐cell lymphoma (PMBL) and classical Hodgkin's lymphoma (cHL), and with a lower frequency in chronic lymphocytic leukemia (CLL)." (PMID 36727672, 2023). "SINE of CRM1/XPO1, a target of chronic lymphocytic leukemia, could effectively covalently bind cysteine residues in XPO1 cargo binding tank to treat the disease and is being tested in clinical trials targeting a wide range of malignancies." (PMID 36120598, 2022). "Deregulation of CRM1/XPO1 is often found in chronic lymphocytic leukemia and other cancers." (PMID 29875770, 2018). "Missense substitutions targeting XPO1 have also been previously reported at a low frequency (<5%) in chronic lymphocytic leukemia (CLL) and esophageal squamous cell carcinoma (ESCC), indicating that these mutations may also play a role in other oncogenic processes." (PMID 28196522, 2017). "Exportin 1 (XPO1/CRM1) is a key mediator of nuclear export with relevance to multiple cancers, including chronic lymphocytic leukemia (CLL)." (PMID 33451349, 2021).
gastric cancer (15 papers, 2014 to 2025). A primary or metastatic malignant neoplasm involving the stomach. "Associated with BC, BlC, PC, and gastric cancer (GC),Uc.63 has an oncogenic role, independently of the host XPO1 gene,inducing proliferation and cell migration, also decreasing apoptosis levels in BC,BlC cell lines." (PMID 36622962, 2023). "Several non-coding RNAs, particularly piRNAs, have been implicated in the biology of gastric cancer and more recently, piRNA biogenesis has been linked to XPO1 activity in a Drosophila model." (PMID 31569391, 2019). "Using the Human Protein Atlas, we found that high XPO1 expression is linked to survival outcomes in all stages of gastric cancer (p < 0.05)." (PMID 31569391, 2019). "Having established that XPO1 is overexpressed in gastric cancer tissue, we then evaluated the impact of knocking down this protein on cellular survival." (PMID 31569391, 2019). "In this report, we demonstrate the critical role of XPO1 in gastric cancer sustenance using diverse sub-types of patient tissues, in in vitro cellular models, 3D models as well as an in vivo xenograft model." (PMID 31569391, 2019). "We demonstrate significant overexpression of XPO1 in a cohort of histologically diverse gastric cancer patients with primary and metastatic disease." (PMID 31569391, 2019). "In this article we demonstrate the therapeutic potential of targeting the nuclear export protein exportin 1/ chromosome region maintenance 1 (XPO1/CRM1) in gastric cancer." (PMID 31569391, 2019). "The continued evaluation of KPT-330 to establish the safety of targeting nuclear export through XPO1 would augment the clinical translation of XPO1 inhibitors for the treatment of gastric cancer." (PMID 30115935, 2018). "In gastric cancer, high expression of XPO1 was shown to have a significant correlation with advanced tumor stage, distant metastasis and poor prognosis." (PMID 30115935, 2018). "The mechanism of XPO1 inhibitor-mediated proliferation inhibition and apoptosis in gastric cancer cells is also determined." (PMID 30115935, 2018). "The current study identified XPO1 as an independent prognosis indicator, as its over expression correlates with poor survival in gastric cancer patients." (PMID 30115935, 2018). "Microarray analysis of clinical samples revealed that XPO1 is overexpressed in gastric cancer as compared to adjacent normal tissues." (PMID 30115935, 2018). "Taken together, our study underscores the therapeutic utility of XPO1 targeting in gastric cancer and suggests the potential benefits of XPO1 inhibition in-combination with chemotherapy." (PMID 30115935, 2018). "XPO1 was found to be overexpressed in gastric cancer as compared to adjacent normal tissues and was correlated with poor survival outcomes." (PMID 30115935, 2018). "We show that targeted inhibition of XPO1 can realign several non-coding RNAs that could also impact gastric cancer cell growth." (PMID 31569391, 2019). "We sought to evaluate whether XPO1 inhibition could affect small noncoding RNA expression in gastric cancer models." (PMID 31569391, 2019). "XPO1 RNA interference suppressed gastric cancer cell growth." (PMID 31569391, 2019). "Together, these results suggest that XPO1 inhibition of XPO1 can significantly reduce gastric cancer cell growth and could be a viable therapeutic target for this disease." (PMID 31569391, 2019). "Since gastric cancer affects both genders, we wanted to know whether there are survival differences that correlate with XPO1 overexpression." (PMID 31569391, 2019). "We next evaluated the expression levels of XPO1 in a panel of gastric cancer cell lines." (PMID 31569391, 2019). "The present study strongly correlates XPO1 expression with poor prognosis in gastric cancer." (PMID 30115935, 2018). "Expression levels of XPO1 was also determined in a panel of 10 gastric cancer cell lines." (PMID 30115935, 2018). "Studies have suggested XPO1 upregulation as an indicator of poor prognosis in gastric cancer." (PMID 30115935, 2018).
gastric cancer (continued). "A prognostic role of the XPO1 protein was established in gastric cancer (GC)." (PMID 25476752, 2014). "Moreover, gene FBXO11, XPO1, SLC3A2, and APC, whose mutation detections may be affected by various tumor purities in gastric cancer, were closely related with cancer occurrence and development." (PMID 33425983, 2020). "Protein XPO1 is positively correlated with cell proliferation and growth transformation, and negatively correlated with poor survival outcomes, which could be a promising molecular target in gastric cancer." (PMID 33425983, 2020). "Moreover, a recent study from our lab has demonstrated that XPO1 may act as a promising molecular target in gastric cancer and blocking it using SINE compounds can have therapeutic significance." (PMID 31905765, 2019). "Here we show that the nuclear export protein, Exportin 1 (XPO1, chromosome region maintenance 1 or CRM1), is a promising molecular target in gastric cancer." (PMID 31569391, 2019). "We confirmed the essential role of XPO1 in cell proliferation and growth transformation using cell lines of other types of cancer, including AGS cells derived from gastric cancer and HUH7 cells derived from liver cancer." (PMID 31088931, 2019). "In the present study, we investigated the therapeutic efficiency of XPO1 inhibition with SINE compounds KPT-185, KPT-276 and KPT-330 in gastric cancer." (PMID 30115935, 2018). "Here, we establish the anti-tumor efficacy of XPO1 inhibitor KPT-330, both in in vitro and in vivo models of gastric cancer." (PMID 30115935, 2018). "The role of XPO1 in gastric cancer has not been examined before and has been examined in liver cancer only minimally." (PMID 31088931, 2019). "Since preclinical evaluation of XPO1 inhibition in combination with chemotherapy yielded promising results in other cancers, we evaluated the combinatorial effect of KPT-330 with irinotecan in gastric cancer." (PMID 30115935, 2018). "Using XPO1 inhibitor KPT-8602 and by small interfering RNA (siRNA) knockdown, we confirmed the essential role of XPO1 in cell proliferation and growth transformation of KSHV-transformed cells and in cell lines of other cancers, including gastric cancer and liver cancer." (PMID 31088931, 2019). "Although KPT-330 is specifically known to target XPO1, we hypothesized that combination treatment of paclitaxel with SINE may perturb additional members of the nuclear transport system to allow for a more enhanced therapeutic effect on gastric cancer cells." (PMID 31569391, 2019).
colorectal cancer (14 papers, 2015 to 2026). A primary or metastatic malignant neoplasm that affects the colon or rectum. "Given XPO1’s involvement in numerous pathways related to colorectal cancer tumorigenesis, eltanexor holds promise as a broad-spectrum chemopreventive agent for high-risk patient populations." (PMID 40601866, 2025). "Collectively, these findings highlight XPO1 as a potent target for colorectal cancer chemoprevention." (PMID 40601866, 2025). "To assess XPO1’s expression in colorectal cancer tumor tissue compared with normal colon tissue, we analyzed The Cancer Genome Atlas Program data through the Gene Expression Profiling Interactive Analysis." (PMID 40601866, 2025). "When we examined XPO1 gene expression in multiple colorectal cancer cell lines, XPO1 mRNA was consistently overexpressed in colorectal cancer cell lines examined." (PMID 40601866, 2025). "In this study, we demonstrate the significant impact XPO1 inhibition has on colorectal cancer tumorigenesis." (PMID 40601866, 2025). "The consistent overexpression of XPO1 further suggests that the overexpression is an early event in colorectal cancer." (PMID 40601866, 2025). "Previous studies and The Cancer Genome Atlas data suggest that XPO1 is consistently overexpressed in colorectal cancer." (PMID 40601866, 2025). "Our findings reveal that eltanexor treatment markedly reduces colorectal cancer cell viability by blocking XPO1’s interaction with cargo proteins and promoting subsequent XPO1 protein degradation." (PMID 40601866, 2025). "For instance, XPO1 has been identified as a critical player in tumorigenesis, with its overexpression noted in several cancers, including pancreatic, lung, and colorectal cancers." (PMID 39882192, 2025). "In this study, we show the XPO1 inhibitor eltanexor acts as an effective colorectal cancer chemopreventive agent both in vivo and in vitro." (PMID 40601866, 2025). "Our analysis of XPO1 expression in multiple colorectal cancer stages and expression in the FAP model Apcmin/+ mouse adenomas suggests that XPO1 overexpression is an early-occurring event in colorectal cancer tumorigenesis." (PMID 40601866, 2025). "When we examined the impact of XPO1 expression on overall colorectal cancer survival, we observed increases in XPO1 expression trend toward poorer survival, particularly in microsatellite-stable colorectal cancer." (PMID 40601866, 2025). "Because of XPO1 interacting with many proteins, the inhibition of XPO1 can lead to the impairment of multiple different hallmarks of cancer; we hypothesized that XPO1 is a viable colorectal cancer chemoprevention target." (PMID 40601866, 2025). "Furthermore, we examined XPO1 expression among stage 1 to 4 colorectal cancer and found that XPO1 was consistently expressed." (PMID 40601866, 2025). "Given that XPO1 is overexpressed in colorectal cancer and its inhibition reduces numerous hallmarks of cancer, we hypothesize that eltanexor will act as an effective chemopreventive agent." (PMID 40601866, 2025). "Furthermore, XPO1 protein expression was examined in colorectal cancer cells treated with eltanexor, revealing a dose-dependent reduction with drug treatment." (PMID 40601866, 2025). "This study aimed to evaluate the association between the overexpression of XPO1 with NF-κB, Ki67 and clinicopathological characteristics in colorectal cancer (CRC) tissue samples and to explore the anti-proliferative effect of KPT-330, as XPO1 inhibitor, in colorectal cancer cell line." (PMID 31870117, 2019). "Various cancers overexpress XPO1, including colorectal cancer, and selective inhibitors of nuclear export compounds, such as eltanexor (KPT-8602), have been developed to target XPO1." (PMID 40601866, 2025).
colorectal cancer (continued). "Forty CRC tissue samples were analyzed by immunostaining for the expressions of XPO1, NF-κB and Ki67 and then the anti-proliferative effect of the KPT-330 was also evaluated in HT29 colorectal cancer cell line." (PMID 31870117, 2019).
hepatocellular carcinoma (14 papers, 2008 to 2026). A malignant tumor that arises from hepatocytes. "Although high XPO1 expression in cancer is commonly associated with a poor prognosis, we show that the outcome of specific cancers, such as hepatocellular carcinoma, can be substantially improved if there is concomitant evidence of NK cell infiltration." (PMID 39178254, 2024). "Furthermore, a recent study showed that an XPO1-derived peptide acts as an activator for NK cells in hepatocellular carcinoma." (PMID 40601866, 2025).
glioblastoma (10 papers, 2014 to 2025). The most malignant astrocytic tumor (WHO grade IV). "This is consistent with previous in vitro studies which showed that XPO1 is degraded after selinexor treatment in human glioblastoma cell lines." (PMID 39682167, 2024). "XPO1 has recently emerged as a viable treatment target for solid malignancies, including glioblastoma (GBM), the most common primary malignant brain tumor in adults." (PMID 30337641, 2018). "Our results show that inhibition of XPO1 reduces cellular viability in glioblastoma cell cultures." (PMID 30337641, 2018). "The XPO1 inhibitor leptomycin B (LMB) and KPT-330 consistently downregulated Mcl-1 but not Bcl-2 or Bcl-xL in a dose-dependent manner in U87 and U251 glioblastoma cells and H1299 NSCLC cells." (PMID 31113936, 2019).
neuroblastoma (9 papers, 2019 to 2025). Neuroblastoma (NB) is the most common solid, extracranial childhood tumor. "High expression of XPO1 has been reported in various tumors, including pancreatic adenocarcinoma, gastric cancer, neuroblastoma, and hematologic tumors, and is strongly associated with poor prognosis." (PMID 36200270, 2023). "Higher XPO1 levels were associated with advanced stage and poor prognosis in neuroblastoma patients." (PMID 34384466, 2021). "This study was the first to demonstrate the significant association of XPO1 overexpression with poor clinical characteristics and prognosis in neuroblastoma patients." (PMID 34384466, 2021). "This study is the first to demonstrated the significant association between overexpression of XPO1 and poor clinical characteristics and prognosis in neuroblastoma patients." (PMID 34384466, 2021). "In summary, our study demonstrated that the overexpression of XPO1 was significantly associated with poor clinical characteristics and prognosis in neuroblastoma patients." (PMID 34384466, 2021). "This could be explained by the inhibition of XPO1 interference with many of the hallmark pathways in neuroblastoma." (PMID 34384466, 2021). "XPO1 is a promising prognostic indicator for neuroblastoma and a novel target for antitumor treatment with selective inhibitor verdinexor." (PMID 34384466, 2021). "Verdinexor, the specific inhibitor of XPO1, suppressed the neuroblastoma cell growth and induced cell apoptosis by FOXO1 and RB1 nuclear accumulation through inhibition of the PI3K/AKT pathway." (PMID 34384466, 2021). "Numerous publicly available gene expression datasets support the recently published findings from a proteomics screen in neuroblastoma that XPO1 is most highly expressed in patients with inferior outcome." (PMID 34944778, 2021). "In an in vitro study, a specific XPO1 inhibitor, verdinexor, induced cell cycle arrest and apoptosis in neuroblastoma cells SH-SY5Y." (PMID 34384466, 2021). "Inhibition of XPO1 by the specific inhibitor verdinexor suppressed neuroblastoma cell growth and induced cell apoptosis through FOXO1 and RB1 nuclear accumulation by inhibiting the PI3K/AKT pathway." (PMID 34384466, 2021). "The specific inhibitor of XPO1 verdinexor suppressed the neuroblastoma cell growth both in vitro and in vivo." (PMID 34384466, 2021). "XPO1 inhibitor Leptomycin B (LMB) decreased the phosphorylation level of FOXO3a via a PI3K-dependent pathway to suppress neuroblastoma cell growth." (PMID 34384466, 2021). "Results showed that the XPO1 selective inhibitor verdinexor (KPT-335) significantly inhibited neuroblastoma cell proliferation in a dose-and time-dependent manner." (PMID 34384466, 2021). "A previous study reported that the second generation XPO1 inhibitor KPT-330 has antitumor effects on neuroblastoma animal models." (PMID 34384466, 2021). "This indicated that the AKT signaling pathway was involved in the transportation of FOXO1 and RB1 by XPO1.Our research confirmed that verdinexor inhibited neuroblastoma proliferation and induced apoptosis through nuclear accumulation of FOXO1 and RB1." (PMID 34384466, 2021). "Taken together, XPO1 was a promising prognostic indicator for neuroblastoma and a novel target for antitumor treatment with selective inhibitor verdinexor." (PMID 34384466, 2021). "Therefore, XPO1 is a promising prognostic indicator for neuroblastoma and represents a novel therapeutic target by the selective inhibitor verdinexor." (PMID 34384466, 2021).